SOX4 (SRY-box transcription factor 4)
Diseases named in the same sentence as SOX4 in open-access papers (continued):
Sharing a sentence is not in itself a finding about the gene and the disease.
tumor (continued). "SOX4 expression was also found to be significantly upregulated in tumor tissue following GEPIA analysis." (PMID 33995626, 2021). "Tumor volume and weight were reduced by silenced HNF1A‐AS1 while co‐transfection of SOX4 rescued the suppressive influence of silenced HNF1A‐AS1 on tumor volume and weight." (PMID 33448691, 2020). "SOX4, one of the sox transcription factors, has been proven as an oncogene and correlated with tumor progression and development." (PMID 32127028, 2020). "CircUBAP2 represents a prognostic marker and contributes to tumor growth and metastasis via modulating miR-361-3p/SOX4 axis in CC, which indicates a potential therapeutic target for CC treatment." (PMID 32760224, 2020). "Consistently, the tumor volume and weight were also smaller in sh-circ-SOX4 group compared with sh-NC group." (PMID 31911754, 2020). "In this study, we found that transcription factor SOX4 promotes tumor growth and metastasis, likely through binding to the promoter of CXCR7 gene and activating its transcription." (PMID 33005101, 2020). "Of these candidate genes, SOX4 was reported be closely with tumor progression, and was selected as a candidate target of METTL14-mediated m6A modification for further study." (PMID 32552762, 2020). "In previous studies, miR-138-5p has been shown to directly suppress tumour progression by targeting cyclin D3 41 and SOX4 42,43." (PMID 32292524, 2020). "Sex-determining region Y-related high-mobility group box 4 (SOX4) is another crucial transcription factor that contributes to tumor cell survival, metastasis, and possibly to the maintenance of cancer stem cell properties." (PMID 33628737, 2020). "In vivo experiments showed that silenced circ-SOX4 was correlated with the decreased tumor size, volume, weight, and ki-67 expression." (PMID 31911754, 2020). "Nude mouse xenograft models revealed that in nude mice injected with cells transfected with HBLV-h-LINC01694, the tumor volume and mass increased significantly, miR-340-5p decreased, and the relative expression of Sox4 mRNA and protein increased." (PMID 32270853, 2020). "SOX4 also appears to be upregulated in various tumor tissues compared with corresponding normal tissues." (PMID 33188157, 2020). "The tumor xenograft assay in nude mice was performed to demonstrate the role of the JPX/miR-25-3p/SOX4 axis in CC." (PMID 32943989, 2020). "In gastric cancer cells, overexpression of MIR211 directly inhibits SOX4 expression and thereby down regulates tumor metastasis, suggesting the involvement of cancer stem cells." (PMID 33628737, 2020). "For example, lncRNA-PAGBC competitively binds to the tumor suppressive microRNAs miR-133b and miR-511 and therefore titrates miRNAs off their binding sites on SOX4 and PIK3R3, which then activates AKT/mTOR pathway in gallbladder cancer." (PMID 32123162, 2020). "SOX4 has been previously demonstrated to contribute to tumor progression by promoting cancer stemness." (PMID 31941033, 2020). "We further investigated the effect of SOX4 on metastasis in vivo by examining metastasis in tumor bearing mice." (PMID 33005101, 2020). "Recent report documents that SOX4 plays a central role in EMT as well as in primary tumor growth and metastasis by directly regulating the expression of a number of genes with critical functions in EMT." (PMID 32090981, 2020). "Further, we performed in vivo experiments to assess the effect of circ-SOX4 on the tumor growth of LUAD." (PMID 31911754, 2020). "Using online tools including TargetScan, miRDB, PicTar and RNA22, and combined with previous studies, we integrated eight putative tumor-suppressor miRNAs targeting SOX4: miR-204, miR-211, miR-212, miR-129, miR-106a, miR-300, miR-25, and miR-32." (PMID 30872583, 2019). "Previously, we and others have suggested that SOX4 overexpression was correlated with poor prognosis and tumor progression through the induction of EMT and metastasis in PCa15,34,40,41." (PMID 30872583, 2019).
tumor (continued). "Multiple studies have demonstrated that SOX4 plays a critical role in modulating the cellular proliferation, migration, invasion of tumor cells." (PMID 30872583, 2019). "We show that SOX4 directly regulates endothelin-1 (ET-1) expression and can thereby promote tumor-induced angiogenesis both in vitro and in vivo." (PMID 30507376, 2018). "This treatment lowered intracellular pH both in vitro and in a mouse xenograft tumor model, depleted cellular ATP, blocked Wnt signaling, downregulated SOX4, and strongly decreased stemness and viability of cancer cells." (PMID 29977599, 2018). "Our data provide novel mechanistic insights into context-dependent SOX4 target gene selection, and uncover a novel pro-oncogenic role for this transcription factor in promoting tumor-induced angiogenesis." (PMID 30507376, 2018). "The pro-oncogenic function of SOX4 has been attributed to a number of key cell-intrinsic processes including cell proliferation, cell-cycle regulation and tumor stemness." (PMID 30507376, 2018). "Since SOX4 does affect multiple processes that affect tumor progression we envision that ET-1 depletion would strongly reduce metastasis formation, but would most likely not abolish metastatic outgrowth completely." (PMID 30507376, 2018). "Primary tumor growth was unaffected by SOX4 depletion and both scrambled control and SOX4 KD mice were sacrificed in the same week." (PMID 30507376, 2018). "Taken together, our global-transcriptional analysis provides mechanistic insight into the contextual nature of SOX4 responses and uncovers a novel role for SOX4 in tumor-induced angiogenesis by direct regulation of ET-1 expression." (PMID 30507376, 2018). "The expression of the transcription factor SOX4 is increased in many human cancers, however, the pro-oncogenic capacity of SOX4 can vary greatly depending on the type of tumor." (PMID 30507376, 2018). "Primary tumor-growth was not consistently affected in vivo by SOX4 depletion, as we observed little consistent difference in tumor growth after SOX4 knockdown." (PMID 30507376, 2018). "Experiments in mice with conditional deletion of SOX4 in stratified epithelia showed resistance to chemical carcinogenesis leading to delayed onset and tumor size reduction." (PMID 30514916, 2018). "We define a ‘core’ SOX4-transcriptional network in mammary epithelial cells that reveals an unexpected role of SOX4 in tumor-induced angiogenesis through direct regulation of Endothelin-1 (ET-1)." (PMID 30507376, 2018). "Conversely, it has been demonstrated that knockdown of the SOX4 gene in xenograft model suppresses tumor growth." (PMID 29977599, 2018). "We analysed Wang's cohort (GSE14520) using R language and Bioconductor, and found high Sox4 expression in liver tumours compared with peri-tumour tissues." (PMID 27553854, 2016). "Sox4 deficiency impaired liver TIC self-renewal in sphere formation assays in vitro and tumour-initiation experiments in vivo." (PMID 27553854, 2016). "We found Sox4 largely rescued the impaired tumour initiation capacities induced by LncSox4 knockdown." (PMID 27553854, 2016). "Tumour-free mice ratios and TIC ratios proved that Sox4 plays an essential role in tumour initiation." (PMID 27553854, 2016). "Taken together, these data implicate SOX4 as a key mediator of the tumor-suppressive effects of miR-31 in this system." (PMID 25644061, 2015). "At the end of experimental period, the tumor size from CaSki/SOX4 was larger than that from CaSki/Mock, and the weights of tumors were 420.88±71.62 and 160.14±26.33 mg, respectively (P<0.05)." (PMID 26583330, 2015). "Ki67 staining was found to be expressed much stronger in the tumor tissues from CaSki/SOX4 cells than that in the tumor tissues from CaSki/Mock cells." (PMID 26583330, 2015).
tumor (continued). "Little is known about the molecular and prognostic significance of SOX4 in OSCC, although one report correlated SOX4 expression with OSCC tumor stage." (PMID 26555193, 2015). "Although SOX4 has been reported to play an important role in regulating cell migration in several tumor types, the mechanisms need to be lucubrated." (PMID 26578818, 2015). "SOX4 roles for promoting tumor progression by accelerating cell growth and proliferation have been reported previously." (PMID 26583330, 2015). "Consistently, ABCG2-positive staining localized in membrane and/or cytoplasm and was found to be much stronger in the tumor tissues formed by the SOX4-overexpressing CaSki cells than that in the tumors formed by the control cells." (PMID 26583330, 2015). "Some studies have reported that SOX4 is involved in the promotion of epithelial-mesenchymal transition (EMT) during tumor metastasis." (PMID 26578818, 2015). "In this study, we found that SOX4 was highly expressed in CC cells and tissues, and overexpression of SOX4 in CC CaSki cells enhanced tumor clone formation and cell proliferation, and accelerated cell cycle progress." (PMID 26583330, 2015). "As a tumor suppressor, introduction of SOX4 into hepatocarcinoma Hep3B and HepG2 cells induced apoptosis via the caspase cascade with caspase-1 activation." (PMID 25366337, 2014). "Our finding that SOX4 acts as a tumor suppressor in GBM is consistent with previously reported roles of SOX4 as a tumor suppressor." (PMID 25366337, 2014). "Further investigation is necessary to understand this discrepancy and to determine the different cellular contexts in cancer cells that turn SOX4 into a tumor suppressor or tumor promoter." (PMID 25366337, 2014). "Our study found that SOX4 acts as a tumor suppressor in GBM cells by induce cell cycle arrest and inhibiting cell growth." (PMID 25366337, 2014). "Similar to TGF-β, SOX4 has a paradoxical function in tumorigenesis potentially acting as both a tumor-suppressor and promoter of tumor progression." (PMID 23301048, 2013). "Conversely, RNAi-knockdown of SOX4 in PDAC cell lines results in decreased expression of SEMA3/Plexin family members and is associated with restricted tumor growth both in vitro and in SCID mice." (PMID 23251334, 2012). "As the results, the expression of SOX4 was observed in both cell nucleus and cytoplasm of tumor cells in PGC samples which was consistent with previous studies, and varied in intensity and extent of staining in different tumors." (PMID 22510499, 2012). "By contrast, the higher the level of SOX4 expression, the better the prognosis for patients with medulloblastomas and other tumor types." (PMID 23285187, 2012). "Our findings also showed that overexpression of nuclear SOX4 in GC tissues was closely correlated with tumor invasion and metastasis." (PMID 23285187, 2012). "In conclusion, our data have provided evidence for the first time that the SOX4 protein is highly up-regulated in tumor cells of PGC tissues." (PMID 22510499, 2012). "Overexpression of nuclear SOX4 appears to be a useful marker to predict outcomes in patients with GC who have received surgical resection of the tumor." (PMID 23285187, 2012). "Quantification of SOX4 mRNA expression by quantitative real-time PCR in 10 tumor and non-tumor pairs of gastric tissues." (PMID 23285187, 2012). "Retroviral insertions were present in the mouse homologs of 10 genes tagged in the zebrafish tumor samples: Brd2, Cirbp, Fgf8, Hexim1, Map2k5, Mmp14, Ncoa2, Slc30a5, Sox4, and Sox5." (PMID 21533036, 2011). "We only observed the association in MSS cancers consistent, with SOX4 being differentially expressed between MSS and MSI tumours." (PMID 19156145, 2009).
tumor (continued). "miR-22, miR-133a, and miR-223 act mainly as tumor suppressors by inhibiting cell proliferation, migration and invasion through the modulation of epithelial–mesenchymal transition (EMT)-associated programs and targets such as SOX4 and ARTN." (PMID 41596525, 2026). "Protein-level analysis also confirmed a similar trend of elevated SOX4 expression in tumor tissues." (PMID 40399256, 2025). "Moreover, CAFs affect MMP degradation function by downregulating SRY-box transcription factor 4 (SOX4), further affecting angiogenesis and tumor metastasis." (PMID 40038745, 2025). "In addition, exposure to the magneticfield in combination with the magnetic scaffold had a statisticallysignificant effect on the expression of specific genes associatedwith anti-inflammatory responses and tumor proliferation and metastasis(NMO1, OCT4, SOX4)." (PMID 40875926, 2025). "The results revealed that SOX4 is significantly overexpressed in tumor tissues." (PMID 40399256, 2025). "In vivo validation using a xenograft tumor formation assay showed that SOX4 knockdown in the HepG2 cell line significantly reduced tumor growth rate and final tumor volume Conversely, SOX4 overexpression in Huh7 cells accelerated tumor growth and increased final tumor volume." (PMID 40399256, 2025). "From this, therefore, we hypothesized that in the pathological process of LGG, ZNF800 activates the cell cycle by interacting with PAX4, SOX4, and so on, from promoting malignant tumor progression." (PMID 40644416, 2025). "Likewise, SOX4 expression positively correlates with tumor invasion ability, and patients with high SOX4 expression are more likely to develop lymph node metastasis." (PMID 38233930, 2024). "We also discovered a novel population of tumor-infiltrating CD24+ cancer-associated fibroblasts (CAFs), suggesting that the CD24/SOX4-centered signaling hub could be a potential therapeutic target." (PMID 38203779, 2024). "Targeting SOX4 therapeutically could potentially prevent the tumor progression towards later clones, but further research is needed since SOX4, being a transcription factor, poses further challenges and risks of off-target effects." (PMID 39659836, 2024). "Notably, this shift of SOX4’s function from pro-tumor to pro-apoptosis is triggered by the suppression of KLF5, which is downregulated by TGF-β-induced SNAIL." (PMID 38331879, 2024). "SOX4 and IL-6 were highly expressed in the tumor stage lesion." (PMID 39963655, 2024). "We identified a tumor stem cell cluster (cluster 0) with Axin2, Sox4, Ccnd2, and Clu expression." (PMID 38893159, 2024). "Additionally, knocking down Ndrg1 in BLM tumor organoids reduced secretory progenitor marker gene expression (Sox4, Atoh1, Dll1, Notch1), but increased enterocyte marker gene expression (Cdhr2, Aqp8)." (PMID 38893159, 2024). "Specifically, the use of the eIF4A inhibitor Zotatifin in TNBC mouse models suppressed the translation of Sox4 and Fgfr1, resulting not only in the inhibition of cell proliferation but also in increased interferon response and remodeling of the tumor immune microenvironment." (PMID 38473804, 2024). "The role of SOX4 in promoting tumor angiogenesis is well-established, but its specific impact on NSCLC angiogenesis remains unclear." (PMID 39349443, 2024). "Additionally, the oncogene SOX4 is prominently featured in our differential analysis of tumor cells." (PMID 39607984, 2024). "Increasing evidence shows that SOX4 is closely related to tumor drug resistance." (PMID 37958409, 2023). "Overall, these results strongly suggest that SOX4 might exert specific and even contrasting functions in different tumor types." (PMID 37958409, 2023).
tumor (continued). "In addition, the repressive effects of temozolomide treatment on Ki67 and VEGF expression in tumor tissues were partially rescued by the overexpression of LINC00470 or SOX4." (PMID 36987665, 2023). "Second, we analyzed the relationship between SOX4 expression and the markers of CD8+ T cells, B cells, neutrophils, macrophages, myeloid dendritic cells, tumor-associated macrophages, monocytes, and natural killer cells, as well as Tfh, Th1, Th2, Th9, Th17, Th22, Treg, and exhausted T cells." (PMID 37958409, 2023). "In our study, we have confirmed that miR-3195 served as a tumor suppressor in OS by targeting SOX4." (PMID 37904207, 2023). "SOX4 is a transcription factor with increased expression in a number of malignancies where its expression is positively correlated with increased cell proliferation, inhibition of apoptosis, and tumor progression." (PMID 37686244, 2023). "Given the uniform and potent downregulation of SOX4 by zotatifin treatment in multiple independent tumor models and cell lines, it will be interesting to explore the possibility that zotatifin might potentiate CAR T therapy." (PMID 37874652, 2023). "High-expressed SOX4 affected tumor development or radioresistance in many cancers." (PMID 36212151, 2022). "Similarly, re‐expressed SOX4 rescued the effects of reduced tumour‐sphere formation capacity after the suppression of NAT10." (PMID 35522942, 2022). "Indeed, SOX4 transcription factor, a member of the SOX (SRY-related HMG-box) family, has been shown to promote EMT in vitro, while SOX4 overexpression in tumor tissue indicated poor prognosis in patients with iCCA." (PMID 35205774, 2022). "RA has been widely used clinically to induce the differentiation of NB tumor cells, and our results showed that RA treatment induced the increased expression of SOX4 and that the expression of SOX4 has a positive correlation with the survival rate of patients with NB." (PMID 36428735, 2022). "Additionally, MMA has been reported to induce SOX4 and initiate transcriptional reprogramming, which can bestow aggressive characteristics to tumor cells." (PMID 36523337, 2022). "Reportedly, SOX4 is vital in the modulation of growth, migration, and invasion of tumor cells." (PMID 35112991, 2022). "To further verify whether hsa_circ_0020714 upregulates the SOX4 expression by sponging miR-30a-5p, we detected the expression of miR-30a-5p and SOX4 mRNA in above 120 NSCLC patient tumor tissues." (PMID 35800365, 2022). "Therefore, we proved that inhibition of Sox4 also can obviously prevent the growth and inflammation of tumor bearing mice mediated by IL-6." (PMID 35513871, 2022). "Considering that both of the atypical E2Fs and SP1/SOX4/Anillin axis are involved in a similar HCC tumor process, we hypothesized some kind of relationship between these cell cycle regulating genes exists." (PMID 35924788, 2022). "Likewise, SOX4 pathway inhibition prevents the emergence of MHC-ILow tumor cells that are also refractory to CD8+ CTL." (PMID 35053449, 2022). "In addition, in vivo experiments revealed that the tumor mass and volume in nude mice were evidently inhibited, and that miR-138-5p enhanced and Sox4 declined after injection of sh-MIR4435-2HG." (PMID 34532282, 2021). "Hence, knockdown of endogenous SOX-4 notably decreases the migration and invasion ability of tumor cells in vitro, thereby leads to reverse of the EMT cascade by increasing E-cadherin." (PMID 34157052, 2021). "This study found that SOX4 expression is significantly upregulated in HCC tumor tissues." (PMID 33995626, 2021). "Correlation analysis showed that SOX4 expression was related to tumor size and tumor TNM stage." (PMID 33824274, 2021).